JAK3 (Janus kinase 3)
Diseases named in the same sentence as JAK3 in open-access papers (continued):
Sharing a sentence is not in itself a finding about the gene and the disease.
ataxia telangiectasia (2 papers, 2022). Ataxia-telangiectasia is the association of severe combined immunodeficiency (affecting mainly the humoral immune response) with progressive cerebellar ataxia. "Sixty-five blood DNA samples were used for control: 25 from patients with ataxia-telangiectasia, 37 - from patients with Nijmegen breakage syndrome, 1 – with X-linked agammaglobulinemia, 2 – with SCID (JAK3 deficiency and DCLRE1C deficiency)." (PMID 36189201, 2022).
Burkitt lymphoma (2 papers, 2021 to 2023). A rare form of malignant mature B-cell non-Hodgkin lymphoma. "In the present study, we chose TG101209, a more specific or selective JAK2 kinase inhibitor (at approximately 30-fold greater selectivity for JAK2 than JAK3), as an exploration of anti-Burkitt lymphoma activity." (PMID 34588425, 2021).
Cerebral ischemia (2 papers, 2022 to 2025). Restriction of arterial blood supply to the brain associated with insufficient oxygenation to support the metabolic requirements of the tissue. "Moreover, immune cytokine IL‐23 (anti‐IL‐23) and the JAK3 inhibitor could protect from cerebral ischemia–reperfusion injury by targeting the immune‐specific JAK2‐STAT3 in the JAK/STAT pathway because they decreased infarct volume more effectively." (PMID 37786415, 2022).
cerebral malaria (2 papers, 2012 to 2022). A sequestration of Plasmodium falciparum in the brain, which can cause coma and/or seizures. "In 2012, Bongfen and collaborators first reported a mutation in the Jak3 gene that generated a protective effect against cerebral malaria." (PMID 35646724, 2022). "The resistance to cerebral malaria in Jak3 mutant mice was largely explained by impaired CD8+ T cell development and responses, as transfer of CD8 T cells from wild type mice restored susceptibility to the infected Jak3 mutant line." (PMID 35646724, 2022).
chronic lymphocytic leukaemia (2 papers, 2015 to 2020). "The IC50 reported for PF956980 against JAK3 is ~4nM, however this compound has been reported to be effective against IL-4-induced cytotoxic resistance in chronic lymphocytic leukaemia cells at concentrations of ~0.3μM in agreement with the potency of PF956980 in the present study." (PMID 26090665, 2015).
chronic lymphoid leukemia (2 papers, 2019 to 2022). "In addition drugs as Ibrutinib (DScore 0.822) and Acalabrutinib (DScore 0.812) Burton’s tyrosine-kinase inhibitors used in chronic lymphoid leukemia and mantle-cell lymphoma shows activity against JAK3, which is mutated in our patient." (PMID 31655559, 2019). "However, adult zebrafish jak3 mutants developed a malignant lymphoid leukemia, which invaded multiple organs like brain, kidney, liver and intestine." (PMID 36291730, 2022).
clear cell renal cell carcinoma (2 papers, 2012 to 2020). "In clear cell renal cell carcinoma, JAK3 acted as a novel biomarker and was associated with immune infiltration." (PMID 33083484, 2020). "Immunohistochemical analysis on tissue specimens from renal clear cell adenocarcinomas highlights in comparison with normal counterparts the absence of γc chain expression and a strong decrease of JAK3 expression (−70%)." (PMID 22363690, 2012).
combined immunodeficiency syndrome (2 papers, 2020 to 2025). A combined immunodeficiency in which other clinical features are present in other organ systems in addition to immunodeficiency. "Deficiency of Jak3 results in defined clinical disorders, particularly, inactivating Jak3 mutations leads to severe combined immunodeficiency syndrome and has been viewed as an excellent therapeutic target for the development of a new class of immunosuppressive drugs." (PMID 40410684, 2025).
cutaneous lupus erythematosus (2 papers, 2016 to 2023). An autoimmune disorder that manifests as different lupus-specific skin disorders; it can occur with systemic lupus erythematosus, or as a singular disease. "In the epidermal layer, JAK3 was overexpressed in all diseases (except cutaneous lupus erythematosus), indicating its crucial role in inflammatory keratinocytes." (PMID 37624299, 2023). "As far as JAK3 and pJAK3 expression is concerned, in the epidermis, it showed a higher expression in all inflammatory diseases except in cutaneous lupus erythematosus." (PMID 37624299, 2023).
diabetic nephropathy (2 papers, 2022 to 2023). "Our network pharmacology results indicated that baicalin might improve diabetic nephropathy through SIRT1, HNF4A, JAK3, and HMGCR." (PMID 35480869, 2022).
endometriosis (2 papers, 2019 to 2021). The growth of functional endometrial tissue in anatomic sites outside the uterine body. "In general, targeting the IL-34/CSF1R/JAK3/STAT6 pathway with a STAT6 inhibitor was an effective means of treating endometriosis in rats." (PMID 31727934, 2019). "In summary, autocrine production of IL-34, mediated by STAT6, promoted the development of endometriosis in vitro and in vivo through the CSF1R/JAK3/STAT6 pathway." (PMID 31727934, 2019). "Further, an IL-34 neutralizing antibody could attenuate CSF1R/JAK3/STAT6 activation and down-regulate VEGF, MMP-2 and MMP-9, eventually leading to suppression of the development of endometriosis in vitro." (PMID 31727934, 2019).
Hepatic fibrosis (2 papers, 2018 to 2020). The presence of excessive fibrous connective tissue in the liver. "We also found significant upregulation of caspase 1 (Casp1), a key inflammation mediator; Janus kinase 3 (Jak 3), a key controller of signal transduction after receptor activation by the common γ chain; and platelet-derived growth factor (Pdgfb), a key regulator of hepatic fibrosis." (PMID 30305319, 2018). "For example, the dysregulated lncRNAs including NONMMUT014792.2, NONMMUT031907.2, NONMMUT061096.2, NONMMUT047510.2 and ENSMUST00000185516 may be co-expressed with TGFβ-1, JAK3, and STAT1, which are reported to be important regulators of liver fibrosis." (PMID 33261628, 2020).
lichen planus (2 papers, 2016 to 2025). A chronic, recurrent, pruritic inflammatory disorder of unknown etiology that affects the skin and mucus membranes. "Studies show JAK1 and JAK3 overexpression in lichen planus (LP) inflammatory infiltrates, implicating JAK signaling in its pathogenesis." (PMID 41523413, 2025).
lung adenocarcinoma (2 papers, 2016 to 2025). A carcinoma that arises from the lung and is characterized by the presence of malignant glandular epithelial cells. "By administering JAK3 inhibitors in combination with osimertinib, we examined the alterations in osimertinib resistance in lung adenocarcinoma cells." (PMID 40713600, 2025). "In conclusion, MCAM induced EGFR-TKI resistance in lung adenocarcinoma by interacting with Integrin β1 and then activating the JAK3 signalling pathway." (PMID 40713600, 2025). "However, to the best of our knowledge, no studies have demonstrated that MCAM may regulate the resistance of lung adenocarcinoma to EGFR-TKIs through the JAK3 signaling pathway." (PMID 40713600, 2025).
metastatic melanoma (2 papers, 2020 to 2024). A melanoma that has spread from its primary site to another anatomic site. "Similarly, a recent study reported a splicing-augmenting mutation in JAK3, linked to decreased JAK3 expression levels, as a potential mechanism of resistance in a patient with metastatic melanoma treated with anti-PD-1 and anti-CTLA-4 combination therapy." (PMID 38829686, 2024).
Nijmegen breakage syndrome (2 papers, 2020 to 2022). Nijmegen breakage syndrome is a rare genetic disease presenting at birth with microcephaly, dysmorphic facial features, becoming more noticeable with age, growth delay, and later-onset complications such as malignancies and infections. "Five had TRECs between zero and 5/μl and were immediately reported, and among them, one Nijmegen breakage syndrome (NBN) with SCID-like phenotype and three classical SCIDs (Artemis, JAK3, and IL2RG) were identified." (PMID 32754152, 2020).
Omenn syndrome (2 papers, 2020 to 2024). An inflammatory condition characterized by erythroderma, desquamation, alopecia, chronic diarrhea, failure to thrive, lymphadenopathy, and hepatosplenomegaly, associated with severe combined immunodeficiency (SCID). "We report two patients with homozygous hypomorphic JAK3 variants and clinical features of Omenn syndrome." (PMID 38598033, 2024). "We investigated homozygous hypomorphic JAK3 mutations in two patients, and expression and function of a novel JAK3R431P variant in Omenn syndrome." (PMID 38598033, 2024). "These activated T-cells can be of maternal origin in SCID with maternal engraftment (JAK3 with maternal engraftment) or can be oligoclonal, expanded T-cells in Omenn syndrome patients (RAG1 Omenn syndrome)." (PMID 32265901, 2020). "Biallelic null or hypomorphic variants in JAK3 cause SCID and less frequently Omenn syndrome." (PMID 38598033, 2024). "SCID patients had disease-causing mutations in RAG1 or RAG2 (n = 4, two of them presented with Omenn syndrome), IL2RG (n = 4, one of them with confirmed maternal engraftment), NHEJ1 (n = 1), CD3E (n = 1), ADA (n = 1), JAK3 (n = 3, two of them with maternal engraftment) and DCLRE1C (n = 1)." (PMID 32265901, 2020).
pemphigus vulgaris (2 papers, 2020 to 2022). Pemphigus is a group of chronic autoimmune skin diseases characterized by blister formations on the outer layer of the skin and the mucous membranes. "That is why the aim of this study was to evaluate the expression of proteins JAK3, STAT2, STAT4, and STAT6 in skin lesions and perilesional area in patients with pemphigus vulgaris as well as in the control group." (PMID 32170648, 2020). "The aim of this study was to evaluate the expression of proteins: JAK3, STAT2, STAT4 and STAT6 in epithelium lesions in patients with pemphigus vulgaris (PV), bullous pemphigoid (BP), oral lichen planus (LP) and chronic ulcerative stomatitis (CUS), as well as in the control group." (PMID 36613766, 2022).
periodontitis (2 papers, 2025). An acute or chronic inflammatory process that affects the tissues that surround and support the teeth. "Inhibition of the JAK pathway using JAK1‐3 and JAK3 inhibitors significantly modulated immune responses and attenuated tissue degradation in a rat model of experimentally induced periodontitis." (PMID 41041963, 2025). "This study aimed to investigate the role of Janus kinase (JAK) signaling in the pathogenesis of periodontitis by evaluating the effects of pharmacological inhibition of JAK isoforms (JAK1 and JAK3) on periodontal inflammation and ligature‐induced alveolar bone loss." (PMID 41041963, 2025). "This study further explored the upstream regulators of Nedd4‐2 and demonstrated that Janus Kinase 3 (JAK3) amplified Wnt3a signalling by phospho‐inactivating Nedd4‐2, thereby suppressing the infiltration of inflammatory cells in P. gingivalis‐induced mice with periodontitis." (PMID 39626954, 2025).
peripheral T-cell lymphoma (2 papers, 2020 to 2025). "We also found mutations in NOTCH1/NOTCH2 and JAK/STAT genes, previously reported to be mutated in peripheral T-cell lymphomas: NOTCH1 (16/71, 22%), NOTCH2 (14/71, 19%), JAK3 (5/71, 7%), and STAT6 (2/71, 3%)." (PMID 31028364, 2020). "The efficacy of ruxolitinib, a JAK3-STAT pathway inhibitor, in peripheral T-cell lymphoma patients has been confirmed, while a clinical trial evaluating ruxolitinib in ENKTL patients is ongoing (NCT02974647)." (PMID 40433378, 2025).
pneumonia (2 papers, 2012 to 2024). An acute, acute and chronic, or chronic inflammation focally or diffusely affecting the lung parenchyma, caused by an infection in one or both of the lungs (by bacteria, viruses, fungi, or mycoplasma.). "We suggest that modulation of the abnormal innate immune inflammation using a selective JAK3 inhibitor could be a novel and valuable strategy for the management of AI-associated severe pneumonia and immune suppression, even though anti-viral therapy is an important first step in recovery." (PMID 22359619, 2012).
pyoderma gangrenosum (2 papers, 2016 to 2025). An idiopathic, rapidly evolving, and severely debilitating disease occurring most commonly in association with chronic ulcerative colitis. "Tan and Tolkachjov (2024) reported that pyoderma gangrenosum lesions exhibit elevated levels of proinflammatory molecules, including various cytokines, interleukins, JAK-1, JAK-2, JAK-3, and interferon gamma." (PMID 40353091, 2025).
sarcoidosis (2 papers, 2024). Sarcoidosis is a multisystemic disorder of unknown cause characterized by the formation of immune granulomas in involved organs. "Currently, the reports of JAKi in treating sarcoidosis have primarily used tofacitinib orally, a JAK1/JAK3 inhibitor, or ruxolitinib, a JAK1/JAK2 inhibitor, topically." (PMID 39345281, 2024). "Interestingly, 79 gene transcripts were upregulated both in sarcoidosis monocytes and macrophages, and these genes were enriched in “Interferon gamma” and “STAT3 Signaling” pathways, with the inclusion of both STAT3 and JAK3 gene transcripts." (PMID 38353578, 2024).
tauopathies (2 papers, 2021 to 2022). "Therefore, the molecular mechanism by which ibrutinib's off‐targets (e.g., EGFR, JAK3, BMX) modulate tauopathy will be explored in a future study." (PMID 33709472, 2021).
type 1 diabetes (2 papers, 2025). "JAK3, in combination with the IL-2 receptor, which was also upregulated in this study, plays a critical role in T cell development and the progression of type 1 diabetes." (PMID 40597598, 2025).
(CAEBV) infection (1 paper, 2017). "Herein, we report an atypical JAK3 deficiency patient who presented with chronic active Epstein–Barr virus (CAEBV) infection and was subsequently identified to possess 2 compound heterozygous JAK3 mutations." (PMID 29049190, 2017).
acne (1 paper, 2026). An inflammatory process of the sebaceous glands which is characterized by comedones, nodules, papules and/or pustules on the skin. "Contrary to what has been said, there are reports that JAK1 and JAK3 have been proven to be overexpressed in acne lesions, so theoretically, inhibition of JAKs should alleviate acne." (PMID 41481132, 2026).
adenoma (1 paper, 2024). A neoplasm arising from the epithelium. "Mean cumulative adenoma numbers also tended to be higher in JAK3+ patients mean ± standard deviation (9 ± 3.61 vs. 2.57 ± 5.42)." (PMID 39507544, 2024). "The results of the sequencing analysis in the patient with the large HGD adenoma, indicated that APC (Adenomatous Polyposis Coli), KIT, and possibly JAK3 were the most likely early drivers of tumorigenesis in these patients." (PMID 39507544, 2024).
allergic conjunctivitis (1 paper, 2021). "Even in the conjunctive structure of ocular tissue, tofacitinib has also been shown to prevent experimental allergic conjunctivitis in BALB/c mice by downregulating the phosphorylation of JAK3/STAT signaling." (PMID 34966823, 2021).
aortitis (1 paper, 2024). Inflammation of the aorta. "Tofacitinib, a JAK inhibitor (JAKi) that predominantly inhibits JAK1 and JAK3 molecules has been shown to ameliorate aortitis due to GCA by inhibiting the action of T lymphocytes." (PMID 38334659, 2024).
autoimmune hepatitis (1 paper, 2024). Hepatitis caused by autoantibodies. "In autoimmune hepatitis, the expression of JAK3 was found to be increased, affecting inflammatory cytokine production." (PMID 38894720, 2024).
brain inflammation (1 paper, 2022). "The present study suggested that feeding with HFD under the intestinal deficiency of Jak3 caused brain induction of hypoxia inducible factor-1 as a mechanism of TLR4-activation-led brain inflammation." (PMID 36145091, 2022).
cardiac sarcoidosis (1 paper, 2025). Sarcoidosis affecting the tissues of the heart. "The concurrent expression of Acetyl-H3K9, Chi3l1, CSF1R, IL4R, TGFß, and Jak3/Stat6 in granulomas of cardiac sarcoidosis promotes the polarization of macrophages toward the M2 phenotype, facilitating anti-inflammatory conditions and driving fibrotic processes." (PMID 40521183, 2025).
chondrosarcoma (1 paper, 2022). A malignant cartilaginous matrix-producing mesenchymal neoplasm arising from the bone and soft tissue.
chordoma (1 paper, 2025). Chordomas are rare malignant tumors arising from embryonic remnants of the notochord in axial skeleton. "As expected, all chordoma cell lines lacked JAK3, which is only expressed in hematopoietic lineages." (PMID 40901948, 2025).
chronic granulomatous disease (1 paper, 2025). Chronic granulomatous disease (CGD) is a rare primary immunodeficiency, mainly affecting phagocytes, which is characterized by an increased susceptibility to severe and recurrent bacterial and fungal infections, along with the development of granulomas. "CYBB deficiency has been associated with chronic granulomatous disease, whereas a lack of JAK3 can generate an increase in proinflammatory cytokines." (PMID 40006915, 2025).
classical Hodgkin lymphoma (1 paper, 2021). "Based on previous studies, LMP1 activates JAK3 and related STAT proteins to improve the activity of the AP-1-dependent PD-L1 enhancer and to upregulate PD-L1 in EBV-positive classical Hodgkin lymphoma (cHL) cells." (PMID 33549103, 2021).
colon adenocarcinoma (1 paper, 2022). "Since HPV infection is suspected to contribute to the emergence of other cancer types (Bladder Urothelial Carcinoma (BLCA), HNSC, Colon adenocarcinoma (COAD), Prostate Adenocarcinoma (PRAD)), an HPV-associated pan cancer analysis of IKZF3, FOXP3, and JAK3 was performed." (PMID 35719936, 2022).
colorectal tumors (1 paper, 2025). "In our analysis of JAK3-mutated colorectal tumors, we observed significantly improved survival among patients diagnosed at Stage I–III compared to those at Stage IV (p < 0.00001)." (PMID 40723258, 2025).
cyst (1 paper, 2018). A sac-like closed membranous structure that may be empty or contain fluid or amorphous material. "Inhibition of either JAK2 or JAK3 prevents germline cyst breakdown and primordial follicle formation." (PMID 29242197, 2018). "Contrarily, both Jak2 and Jak3 mRNA levels increased in a time-dependent manner during cyst breakdown and the establishment of the primordial follicle pool." (PMID 29242197, 2018).
cystitis (1 paper, 2023). Inflammation of the urinary bladder. "Increased expression of pSTAT3 after CYP treatment has already been shown in a rat model of cystitis, and the inhibition of JAK3 activity has been proven beneficial in reducing the CYP-induced inflammation in rat ulcerative cystitis." (PMID 36982831, 2023). "The RNA seq data showed significant enrichment of the JAK/STAT pathway, whereas the downstream validation of the identified DEGs revealed JAK3 and STAT3 as the key signaling molecules in CYP-induced chronic cystitis." (PMID 36982831, 2023). "Despite higher basal values of Jak1 vs. Jak3 mRNA in the bladders of Ctrl animals, it appears that the JAK/STAT pathway is not activated via JAK1 in CYP-induced cystitis." (PMID 36982831, 2023).
dermatitis (1 paper, 2023). An inflammatory process affecting the skin. "Correlations were also calculated between the severity of dermatitis (CADESI scores) and semiquantitative measurements of the intensity of scoring for JAK1 and JAK3." (PMID 37624299, 2023).
dysplasia (1 paper, 2022). A usually neoplastic transformation of the cell, associated with altered architectural tissue patterns. "In contrast, mutations in JAK3 (Janus kinase 3), MET, and FBXW7 (F-Box and WD repeat domain containing 7) were found only in non-progressing dysplasia, but absent in progressing dysplasia and LSCC cases." (PMID 35406495, 2022).